IGFBP5 (insulin like growth factor binding protein 5)
Diseases named in the same sentence as IGFBP5 in open-access papers (continued):
Sharing a sentence is not in itself a finding about the gene and the disease.
tumor (continued). "Using three spatially-enriched marker genes for each tumor subregion (CT: BCAN, CSPG5, TOP2A; Pseudo: HILPDA, IGFBP5, LGALS3; and MVP: MGP, LUM, THBS1) we identified distinct sub-populations of malignant cells from the scRNA-seq data." (PMID 41366031, 2025). "IGFBP5 reduction produces comparable results, confirming that DIRC3 mediates tumour suppression via IGFBP5 activation." (PMID 41463281, 2025). "Notably, IGFBP5 levels in fibroblasts were highly diverse across samples and anatomic sites, and it is tempting to speculate that such diverse cells may provide different effects on tumor growth." (PMID 40234830, 2025). "According to ingenuity pathway analysis, ANO1 modulates the antiangiogenic factor insulin-like growth factor-binding protein 5 (IGFBP5), which in turn regulates IGF/IGFR signalling in the tumour microenvironment and hence promotes tumour growth." (PMID 40396170, 2025). "Many tumor suppressors and oncogenes modulated by H2A.J play important roles in the regulation of energy metabolism (IGFBP3; IGFBP4; IGFBP5; AKR1B1; SOD2)." (PMID 39062630, 2024). "In conclusion, IGFBP5 increases GBM invasion and promotes tumor growth through the ROR1/HER2-CREB signaling axis." (PMID 36949068, 2023). "Since our results suggest that IGFBP5 promotes GSC invasion and tumor progression, we subsequently assessed the potential therapeutic target role of IGFBP5 in GBM." (PMID 36949068, 2023). "We then examined the effect of IGFBP5 depletion on GSC invasion and tumor progression by intracranial injection into mice with X01 GSCs transduced with shCtrl or shIGFBP5." (PMID 36949068, 2023). "Several factors, including EZH2, SFTPC, IGFBP5, ELN and EDN2, are regulated by NFIB, which have considerate values in the tumour microenvironment, advancing cancer impulsiveness, angiogenesis, migration and spread." (PMID 37845675, 2023). "Ratios of the three AAbs, in particular IGFBP5-AAb and HAPLN1-AAb, noticeably declined at 3 and 12 months after tumor resection (respectively), albeit the reduction in the ratio of TYMS-AAb was not statistically significant." (PMID 36139323, 2022). "Compared to fibroblasts from normal tissues, the top upregulated genes in tumor-derived fibroblasts were CXCL8, CXCL2, CCL2, CXCL3 and CXCL1, and the top downregulated genes were IGFBP5, PTGDS, CCN5, CFD, and RAMP1." (PMID 36357663, 2022). "Of the cytokines analysed, nine (CD30L, CCL11, CCL24, IGFBP5, IL-4, IL-13, MIP-3ß, CXCL4 and TPO) were significantly more abundant in 4T1 primary tumours than in 67NR primary tumours (Fig. 4aiii)." (PMID 33795809, 2021). "When combining LAT1 and IGFBP-5 expression, high LAT1/high IGFBP-5 score correlated with the advanced pT stage (P = 0.0001), advanced tumour grade (P = 0.0026), high LDH (P = 0.0064), and high NLR (P = 0.0070)." (PMID 31992742, 2020). "Based on our study, we propose that IGFBP5 is regulated by TGF-β and plays a role in tumor suppression." (PMID 31886201, 2019). "IGFBP5 knockdown partly abrogated tumor suppressive effect of PKNOX2, indicating that the function(s) of PKNOX2 are dependent on IGFBP5." (PMID 30745575, 2019). "The changes observed in the expression of IGFBP5 and TFF3 correlated with reductions in tumor volume in primary tumors treated with tamoxifen." (PMID 20569502, 2010). "SOCS1 and IGFBP5, which were upregulated by HIF-1alpha at the mRNA level, are closely related with biological properties of tumor (as we will describe in the discussion)." (PMID 20003295, 2009). "After normalization to anti-BSA levels, standardized ratios of anti-AGR2, anti-HAPLN1, anti-IGFBP5, and anti-TYMS were significantly higher in malignant and early-stage CMTs, suggesting selective amplification of tumor-specific immune responses despite global immune suppression." (PMID 41562247, 2026).
tumor (continued). "Notably, intervening with PD1 blockade and PDT during the OPMDs stage hindered the formation of the tumor‐promoting microenvironment, resulting in decreased Treg proportion, reduced S100A8 expression, and increased Fib_Igfbp5 proportion." (PMID 38962427, 2024). "This analysis revealed that seven cell populations exhibited a significant correlation with poorer patient outcomes, including tumor cell cluster 3 (highly expressing S100A2), cluster 8 (TK1), cluster 10 (PTTG1), cluster 12 (IGFBP5), cluster 13 (ISG15), cluster 16 (UPP1), cluster 17 (IL13RA2)." (PMID 38331898, 2024). "Similarly, after their culture with ECs, IL30-overexpressing PCs showed a dramatic upregulation of a wide range of oncogenes, which included CCND2, EGR3, IGFBP5, KLK3, PDLIM4, PTGS1 and SHBG and a few tumor suppressors, such as GPX3, FOXO1, MAX and NKX3-1." (PMID 38087324, 2023). "Moreover, both lentivirus-mediated IGFBP5 knockdown and nanocapsule-mediated Cas9/sgIGFBP5 delivery significantly compromise GSC invasion and extend the survival of orthotopic tumor-bearing mice." (PMID 36949068, 2023). "The knockdown of IGFBP5 expression in 772 GSCs suppressed GSC invasion, as well as the expression of the target genes ETV5 and FBXW9, and tumor volume, while significantly prolonged the survival of the mouse." (PMID 36949068, 2023). "Notably, in the invasive tumors caused by ERBB2 and ERBB3, THE insulin-like growth factor 2 (IGF2) and insulin-like growth factor binding protein 5 (IGFBP-5) are highly expressed, and these growth factors are very important for tumor growth." (PMID 35990843, 2022). "Low miR-204-5p expression is observed in PTC tissue samples compared to adjacent non-cancer tissue, with a parallel increase in IGFBP-5 expression, suggesting that the tumor-suppressor role of miR-204-5p in PTC depends on IGFBP-5 regulation." (PMID 35597813, 2022). "IGFBP5 methylation was not changed between tumor and adjacent normal tissue, however IGFBP5 expression was positively correlated with G2 tumor stage and ER+ patients." (PMID 36465383, 2022). "Levels of TYMS-AAb, IGFBP5-AAb, and HAPLN1-AAb all declined after tumor resection." (PMID 36139323, 2022). "Some showed that IGFBP5 played a negative role in tumor progression by suppressing tumor cell proliferation and metastasis." (PMID 34362467, 2021). "Additionally, IGFBP5, RBMX and TAGLN2, had consistently investigations in peers’ mechanical studies that the three genes were upregulated and promoted tumor metastasis." (PMID 34446747, 2021). "In addition, miR-137 expression was significantly increased, and IGFBP5 expression was reduced in tumor tissues of sh-TUG1-1 group compared with that of sh-NC group (p < 0.01 for miR137, p < 0.01 for IGFBP5)." (PMID 34362467, 2021). "IGFBP-5 and other IGFBP family members have been reported to induce premature senescence in human fibroblasts and endothelial cells and to suppress the growth of several types of tumor cells." (PMID 32843583, 2020). "IGFBP5 can play various roles during tumor progression, sometimes in absence of IGFs, supporting the existence of some IGF-independent activities." (PMID 28882129, 2017). "IGFBP5 expression level was not statistically different between tumor and normal tissue (p = 0.2125)." (PMID 26569312, 2015). "In summary, IGFBP-5 was highly expressed in CIN, and it may participate as a tumor suppressor in the occurrence and development of cervical lesions." (PMID 19476635, 2009). "However, recent studies have revealed that IGFBP5 possesses a multitude of functions independent of IGFs, including the suppression of lipid deposition, aging, promotion of tumor progression, and osteogenesis." (PMID 40873948, 2025). "Importantly, using a tumor-specific targeting and penetrating nanocapsule-mediated delivery of CRISPR/Cas9-based IGFBP5 gene editing significantly suppressed GSC invasion and downstream gene expression, and prolonged the survival of orthotopic tumor-bearing mice." (PMID 36949068, 2023).
tumor (continued). "However, as in MEFs in the present study, suppression of proliferation by IGFBP5 knockdown was also observed in human tumor cells and non-tumor cells, while the opposite was observed in several lines of cancer cells." (PMID 35378512, 2022). "Studies of IGFBP-5 in renal diseases are rare and non-systematic, however, its role in tumor migration, proliferation and tissue fibrosis suggests that IGFBP-5 might be a potential maker which can not be ignored in kidney disease." (PMID 35002740, 2021). "The functional role of IGFBP5 has not been fully clarified, but it may play a role in tumor dormancy, among others in GBM." (PMID 27782828, 2016). "Given that IGFBP5 inhibited cancer metastasis and characteristic morphological changes were observed in A375 and A2058, we investigated whether IGFBP5 plays a role in regulating EMT, a critical event in tumor invasion and progression." (PMID 26010068, 2015). "Simon and his colleagues found that DOG1 regulated the anti-angiogenic factor IGFBP5, leading to the modulation of IGF/IGFR signaling in the tumor microenvironment, which did not involve KIT expression and KIT-dependent pathways." (PMID 31100836, 2019). "We found an inverse correlation between PAPP‐A levels and IGFBP‐5 where no patient in the nulliparous group had tumor that had both high PAPP‐A and low IGFBP‐5, while 50% of patients who had children did." (PMID 26951623, 2016).
cancer (91 papers, 2008 to 2025). A tumor composed of atypical neoplastic, often pleomorphic cells that invade other tissues. "HDFs treated with y-27632 acquire a senescence-associated secretory phenotype (SASP), converting them to cancer-associated fibroblasts (CAF) which can be inhibited by IGFBP-5 knockdown." (PMID 41226289, 2025). "Previous studies have implicated IGFBP5 in cancer inhibition by temporally inactivating the insulin-like growth factor receptor, and JUN has been linked to increased tamoxifen sensitivity through protein kinase C activation." (PMID 38791962, 2024). "Altogether the findings reviewed here indicate a need for a more comprehensive evaluation of IGFBP5 to understand its association with poor outcomes in cancer patients and identify new potential markers and/or therapeutic avenues." (PMID 36465383, 2022). "Particularly fibroblasts, which in cancers are found in a modified form, called cancer-associated fibroblasts (CAFs), are a major source of secreted IGFBP5 protein in normal tissues." (PMID 36093095, 2022). "IGFBP5 has also been shown to drive premature cellular senescence in fibroblasts which results in a phenotype similar to cancer-associated fibroblasts (CAFs)." (PMID 36465383, 2022). "A recent study reported that IGFBP5 was highly expressed in a variety of cancers, promoted cancer occurrence and development, and was implicated in radiotherapy and chemotherapy resistance, but its significance in endothelial cells warrants further research." (PMID 34745098, 2021). "Despite increasing number of studies have shown that IGFBP5 has been associated with various types of cancers, its function in the progression of cancer is controversial." (PMID 32127912, 2020). "In turn, DIRC3 dependent regulation of IGFBP5 impacts the expression of genes involved in cancer associated processes and is needed for DIRC3 control of anchorage-independent growth." (PMID 31881017, 2019). "It has been reported that the cancer-protective T allele of rs4442975 creates a stronger interaction with IGFBP5 than the G allele, resulting in increased IGFBP5 expression." (PMID 27835577, 2016). "IGFBP5 has been demonstrated to be associated with the malignant progression of many cancers." (PMID 41282023, 2025). "Elevation of IGFBP5 secretion plays a role in cancer progression and could be associated with poor prognosis." (PMID 37240298, 2023). "Moreover, we also discovered that DIRC3 and IGFBP5 common target genes are enriched for regulators of cancer associated processes such as cell migration, proliferation, metabolism and mesenchymal cell differentiation." (PMID 31881017, 2019). "Overexpression of IGFBP2 and IGFBP5 have been associated with poorer cancer prognosis." (PMID 29758070, 2018). "Targets of hsa-miR-532-5p such as runt-related transcription factor-3, insulin-like growth factor-binding protein-5, and von Hippel-Lindau were proved to be associated with angiogenesis in many types of cancer." (PMID 30662454, 2018). "In this respect it is interesting that a recent report demonstrated that co-culture of MCF-7 with carcinoma associated fibroblasts (CAFs) resulted in decreased IGFBP-5 mRNA expression in this BC cell line together with development of resistance to the SERD fulvestrant." (PMID 27050076, 2016). "Interestingly, population-based association studies in humans detected a significant association between cancer risk and SNPs mapping in a 50-kb interval encompassing the IGFBP5 and IGFBP2 genes." (PMID 22973541, 2012). "Two genes, Igfbp5 and Igfbp2, residing in this locus and belonging to the insulin-like growth factor binding protein family were expressed at significantly greater levels in normal lung tissue from cancer-resistant Car-R mice than in cancer-susceptible SWR/J mice." (PMID 22973541, 2012).
cancer (continued). "In an elegant study using two model organisms for cancer cachexia, it was shown that ImpL2 in Drosophila, a direct homolog to IGFBP-5 in mammals, is under the regulation of HIF-1α and directly promotes muscle loss." (PMID 41226289, 2025). "Further analysis of metabolites with consistent temporal trends identifies eicosapentaenoic acid (EPA) as a key metabolite, potentially exerting anti‐inflammatory and anti‐cancer effects by inhibiting insulin‐like growth factor binding protein 5 (IGFBP5)." (PMID 39840505, 2025). "Globally, our findings highlight the potential of IGFBP5 as a promising therapeutic target for age-related diseases and cancer." (PMID 38351010, 2024). "And for the majority of the cancers, IGFBP3, IGFBP4, IGFBP5, IGFBP6 and IGFBP7 were significantly positively associated with stromal, immune as well as ESTIMATE scores including COAD, PCPG, PRAD, READ and STAD." (PMID 37088808, 2023). "Nevertheless, the reports of the role of IGFBP5 in cellular growth are contradictory, suggesting a complex role of IGFBP5 in cancer cells, as it can either stimulate or inhibit cell proliferation in various cell types." (PMID 37620794, 2023). "Evidence has been accumulated that IGFBP5 plays a role in the responsiveness to anti-cancer drugs in BC." (PMID 36093095, 2022). "In this section, we will review the role of IGFBP5 in developmental biology as well as its role in non-cancer diseases to highlight some of the functional characteristics of IGFBP5 that make it a prime candidate for investigation in cancer." (PMID 36465383, 2022). "circPIP5K1A downregulates miR-661, which then increases expression of IGFBP5 to promote cancer progression." (PMID 36465383, 2022). "C-terminus of IGFBP5 exhibits anti-cancer activity through inhibition of angiogenesis by down-regulating VEGF." (PMID 36465383, 2022). "The expression level of IGFBP5 is lower in normal breast, in normal tissue adjacent to the cancer lesion and in benign breast lesions." (PMID 36093095, 2022). "Accordingly, factors (IGFBP5, CLCF1 and IL6) reported to be secreted by cancer-associated fibroblasts (CAFs) showed higher expression level in the high-risk group." (PMID 35711936, 2022). "The varying expression levels of IGFBP5 observed in cancer cells lines is also observed in patient samples in previously published datasets." (PMID 36465383, 2022). "A recent study in the field of cancer biology performed with mouse embryonic fibroblasts identified IGFBP5 as a secreted, mTORC1 downstream effector protein that inhibits the function of IGF-1." (PMID 35513854, 2022). "IGFBP5 promotes the production of secreted matrix proteins such as collagens and glycosaminoglycans and can be associated with the matrix indicating that it could assist in the “docking” of cancer cells to distant sites, which is an example of one of the proteins IGF-independent mechanisms." (PMID 36465383, 2022). "Studies of IGFBP5 in cancer have resulted in divergent outcomes, where some results suggest it is pro-tumorigenic, and others indicate it is anti-tumorigenic." (PMID 36465383, 2022). "IGFBP5 has numerous diverse functions that are important in cancer progression, and the signalling pathways modulated by IGFBP5 and their resultant phenotypes are implicated in five out of ten of the updated Hallmarks of Cancer that were expanded upon in 2011." (PMID 36465383, 2022). "This review will summarize the IGF system and its regulation by IGFBPs, discuss the unique role of IGFBP5 in diseases that share important characteristics with cancer, and expand on what is known about IGFBP5 in cancer progression." (PMID 36465383, 2022). "Although IGFBP5 has several established mechanisms in cancer cells, the investigation of IGFBP5 in cancer progression should be expanded to include more components of the TME." (PMID 36465383, 2022).